CTLA4 (cytotoxic T-lymphocyte associated protein 4)
Diseases named in the same sentence as CTLA4 in open-access papers (continued):
Sharing a sentence is not in itself a finding about the gene and the disease.
tumor (continued). "Therefore, it could be proposed that this anti-CTLA-4 Ab can exhibit anti-tumor effects, at least partially, by enhancing Th1 function without depletion of Tregs." (PMID 39106430, 2024). "While targeting of CD200, TIGIT, and LAG3 is less established in GBM treatment, these targets should be highly considered for future drug development as they appear to be present in GBM and may serve as a strong alternative target should a patient’s tumor express low amounts of PD-1/PD-L1 or CTLA4." (PMID 39409893, 2024). "CTLA-4 and PD-1 activate immune reactions to tumor cells by blocking different pathways; therefore, dual administration of both ICIs may precipitate powerful anti-tumor reactions." (PMID 38570507, 2024). "Interestingly, recent data suggests that the inclusion of a CTLA4 inhibitor in conjunction with a MUC1 mRNA nanovaccine enhances the therapeutic impact of the anti-CTLA-4 monoclonal antibody and adjusts the immune resistance within the tumor immune microenvironment (TME)." (PMID 38397971, 2024). "We show with high statistical significance that 177Lu-SN201 is superior at suppressing the tumor growth not only compared to vehicle but also to the commonly used cancer drugs paclitaxel, niraparib, carboplatin, and the combination of the immune checkpoint inhibitors anti PD-1 and anti-CTLA-4." (PMID 38837077, 2024). "Since anti-CTLA-4 and anti-PD-1 employ distinct biological pathways to restimulate lymphocytic functions, various therapeutic strategies have combined them to extract synergistic anti-tumor effects, leading to superior clinical outcomes compared to monotherapies." (PMID 38673829, 2024). "Although immunotherapies targeting programmed cell death protein 1 (PD-1) or cytotoxic T-lymphocyte-associated protein 4 (CTLA-4) have shown efficiency in certain tumors, their consistent failures in the case of GBM are attributed to its classification as an “immunologically cold” tumor." (PMID 38720342, 2024). "However, the interaction of CD86 with CTLA-4, a regulatory receptor also present in some T cells, can suppress the activation of these effector cells, contributing to immunosuppression and allowing the tumor to evade immune surveillance." (PMID 38791312, 2024). "Furthermore, T-regs also may interact with CD11b+ monocytes to alter distant tumor immunity and subsequently suppress PD-1 and CTLA-4 co-expression in CD8+ T-cells in LvM." (PMID 38643348, 2024). "Therefore, blocking CTLA-4 on Tregs may disrupt this suppression and lead to increased immune activation against tumor cells." (PMID 38410760, 2024). "Furthermore, comparing PD-1 or CTLA-4 expression between immune cells bound to tissues and in PBMCs may help address scientific questions regarding how these molecules affect tumor progression." (PMID 38672574, 2024). "Additionally, oxidative stress upregulates immune checkpoint molecules, such as programmed death-1 (PD-1), its ligand PD-L1, and cytotoxic T-lymphocyte-associated protein 4 (CTLA-4), which, while critical for preventing autoimmunity, are co-opted by cancer cells to evade anti-tumor immune responses." (PMID 39766214, 2024). "Conversely, CD80/CD86-targeted CAR-T (CTLA4-CAR), which comprises the extracellular and transmembrane portions of human CTLA4, the cytoplasmic region of human CD28, and the intracellular domains of human CD3z, was designed to destroy CD80/CD86-associated tumor cells in vitro and vivo." (PMID 37457699, 2023). "Glycolysis is essential for effector T cell function; therefore, upregulation of PD-1 and CTLA-4 could be detrimental to anti-tumour immunity and may reflect the skewing of T cells toward an altered phenotype facilitated by PD-1 and CTLA-4 metabolic reprogramming." (PMID 36445478, 2023). "Furthermore, the in vivo anti-tumor results showed that PEGylated CMS@Gox + 1064 nm + anti-CTLA4 therapy could remove the primary tumor and significantly inhibit the growth of distant tumors." (PMID 37064867, 2023).
tumor (continued). "For T cell checkpoint targets such as VISTA and CTLA-4, activity both in the immune synapse and in activated lymphoid microenvironments may represent a significant secondary locus of action that contributes to their anti-tumor activity." (PMID 37753969, 2023). "In addition, a PD-1 and CTLA-4 combination blockade has been shown to increase effector Teff infiltration, resulting in highly advantageous Teff-to-regulatory T-cell ratios within the tumor." (PMID 38136421, 2023). "However, the association between the expression of CTLA-4 in antigen-presenting cells (APC) of the tumor microenvironment and Ann Arbor stage at presentation was not significant (χ2 test for significance; χ2value=4.613; p value=0.594)." (PMID 37305822, 2023). "Recently, the concept of synergistic radiation therapy and immunotherapy was strengthened by showing that tumor cells that were treated with noncurative doses of irradiation induced somatic mutations that were successfully targeted by anti-PD-1/anti-CTLA-4 immunotherapy." (PMID 37247078, 2023). "The alternative immune checkpoints such as PD-1, CTLA-4, T-cell immunoglobulin domain and mucin domain-3 (TIM-3), B- and T-lymphocyte-associated (BTLA), which were detected on cytotoxic CD8+ T cells with a gradual and continuous upregulation, impair the recognition and killing of tumor cells." (PMID 36776832, 2023). "Therefore, we speculate that CD44 of tumor cells may affect the expression of CTLA-4 of T cells to help tumor cells immune evasion." (PMID 37316699, 2023). "These agents block proteins and ligands, such as cytotoxic T-lymphocyte-associated protein-4 (CTLA-4) and programmed cell death protein 1/programmed cell death ligand 1 (PD-1/PD-L1), that ordinarily inactivate cytotoxic T cells, which are important players of the immune system against tumor cells." (PMID 37958355, 2023). "CTLA-4 blockade could induce an abscopal effect on metastatic lesions, when primary tumors were locally irradiated, with the effect showing a correlation with the frequency of tumor-specific IFNγ-secreting CD8 T cells." (PMID 36831435, 2023). "The model incorporates both the susceptible and infected tumor populations, natural killer cell population, virus population, tumor-specific immune populations, virus-specific immune populations, tumor suppressive cytokine IFN-g, and the effect of immune checkpoint inhibitor CTLA-4." (PMID 36766849, 2023). "Therefore, increased anti-PD-1 and anti-CTLA-4-induced inflammatory T-cell activation may lead to tumor resistance mechanisms and carditis." (PMID 36831655, 2023). "When adoptively transferred into T cell-deficient mice, CTLA-4-/- Treg could provide tumor protection, in contrast to CTLA-4+/+ Treg, indicating that CTLA4-deficient Treg did not have suppressor function but rather acted as T effector cells." (PMID 37342323, 2023). "Last, we must also emphasize that the modulation of COX-2 expression, as a representation of chronic inflammation, may require a prolonged therapeutic regimen, which could promote synergism with anti-CTLA-4 to improve NK cell activity against HGSOC tumor cells." (PMID 38201508, 2023). "Anti-CTLA-4 antibodies inhibit the binding between CTLA-4 and B7, which could prolong T cell activation, restore T cell proliferation, and establish an immune response to tumor-associated antigens (TAAs)." (PMID 36845142, 2023). "Besides, they identified a cluster of cytotoxic GZMB CD4+ T cells that expressed high levels of PDCD1 and CTLA4, suggesting that this population could be involved in the anti-tumor response after immunotherapy." (PMID 36414693, 2023). "Interestingly, combined treatment with CTLA-4 mAbs (Ipilimumab) and PD-1 (nivolumab) mAbs can kill tumor cells to the greatest extent and delay the occurrence and development of tumors, including metastatic melanoma, metastatic renal cell carcinoma, colorectal cancer with MSI-H and MMR aberrations." (PMID 37936703, 2023).
tumor (continued). "Additionally, lymphocyte-mediated killing of OE33 R cells was negatively correlated with the frequency of CTLA-4+CD8+ T cells suggesting that the CTLA-4 axis may be hindering the ability of expanded lymphocytes to kill tumour cells as well." (PMID 37359545, 2023). "Research has shown that tumor infiltrated lymphocytes (TILs) tend to be hypofunctional due to the hypoxic conditions and upregulation of immune inhibitory molecules, such as PD-1 and CTLA-4, as well as suppression from the myeloid-derived suppressor cells (MDSCs) and regulatory T cells (Tregs)." (PMID 37349298, 2023). "Although studies have shown that molecular targeting of vascular endothelial growth factor, platelet-derived growth factor, and inhibitor (PD1-PD-L1/CTLA4) to inhibit immune checkpoints can improve prognosis to a certain extent, tumor cells may grow immune to the new anti-tumor drugs." (PMID 36755568, 2023). "Thus, inhibiting Gr-1( +) and CTLA-4 can improve tumor immune response." (PMID 37978469, 2023). "Depleted and dysfunctional tumor-infiltrating lymphocytes (TILs) in HNC cases are characterized by upregulation of several checkpoint markers, such as programmed cell death 1 (PD-1), lymphocyte-activating gene 3 (LAG-3), and cytotoxic T-lymphocyte-associated protein 4 (CTLA-4)." (PMID 37511510, 2023). "Furthermore, by combining SLC-0111 with anti-CTLA-4 and anti-PD-1 antibodies, they demonstrated that the triple therapy could target tumor-induced central necrosis and reduce the burden of lung metastasis." (PMID 37860188, 2023). "Moreover, the SYNGR2high group was more likely to gain benefits from anti-PD1/PDL1/PDL2 therapies in CESC, COAD, KICH, other tumor tissues, and respond to anti-cytotoxic T-lymphocyte associated protein 4 (CTLA-4) therapy in BRCA, CESC, COAD, and other tumor tissues." (PMID 37170221, 2023). "Furthermore, both Treg and tumor cells express programmed death-ligand 1 (PD-L1) and CTLA-4." (PMID 38044996, 2023). "Moreover, in vitro studies indicate that combined immunotherapy with a vaccine and an anti-CTLA-4 monoclonal antibody can significantly enhance the anti-tumour immune response compared to the vaccine or monoclonal antibody alone, and MUC1 can be a target for CAR-T therapy in HNSCC." (PMID 36980527, 2023). "However, several immune checkpoint molecules, mainly cytotoxic T-lymphocyte-associated antigen-4 (CTLA-4), programmed death-1 (PD-1), and programmed death-ligand 1 (PD-L1), suppress T-cell-mediated antitumour immune responses in the tumour microenvironment (TME)." (PMID 36949951, 2023). "This suggests that overweight individuals may have an increased CTLA-4 expression, which in turn inhibits T-cell activation and increases the risk of trastuzumab non-responsiveness and tumor recurrence." (PMID 38406785, 2023). "The blockade of CTLA-4 and PD-1/PD-L1 in combination may, therefore, synergistically hinder Treg-mediated immune suppression, thereby effectively enhancing immune responses, including tumor immunity." (PMID 36901944, 2023). "In addition, tumor cells can upregulate CTLA-4, PD-1 or PD-L1 to suppress immune cells." (PMID 36611126, 2023). "Also, patients with large tumours (>40 mm) had higher CTLA-4 expression (70% vs. 53.8%)." (PMID 37761948, 2023). "Interestingly, we observed a significant increase in the frequency of H-2Kb SIINFEKL tetramer positive CD8+ T cells upon domatinostat, and to a larger extent in domatinostat + anti-PD-1 + anti-CTLA-4–treated mice, indicating an increase in tumor-reactive T cells upon treatment." (PMID 36920329, 2023). "T cells within the tumor microenvironment often show features of functional exhaustion and this is typically associated with expression of programmed cell death protein 1 (PD-1), often in association with additional checkpoint markers such as Tim-3, LAG-3, or CTLA-4." (PMID 36689623, 2023).
tumor (continued). "Blocking of inhibitory checkpoints such as cytotoxic T-lymphocyte-associated protein 4 (CTLA-4), programmed cell death protein 1 (PD-1), programmed cell death ligand 1 (PD-L1) or lymphocyte activation gene 3 (LAG-3) can enhance the function of tumor-reactive T cells and induce anti-tumor immunity." (PMID 37760634, 2023). "Furthermore, preclinical data has indicated that CTLA-4-blockade has a significant effect on boosting the anti-tumor response, suggesting that targeting CTLA-4 could serve as a viable method for activating cytotoxic T-lymphocytes (CTLs) in cancer therapy." (PMID 37064017, 2023). "CTLA-4 expression on regulatory T cells plays a pivotal role in hindering anti-tumour immunity by promoting regulatory T cell function, which suppresses antigen-presenting cells by depleting immune stimulating cytokines, producing immunosuppressive cytokines and constitutively expressing CTLA-4." (PMID 36445478, 2023). "When compared with control, ZVI-NPs could inhibite tumor growth by 4 times and enhance lymphocytic immunity by decreasing the proportions of PD-1+ cells and CTLA4+ cells in tumor-infiltrating CD8+ T cells by 20% and reducing the amount of regulatory T cells (Tregs) by half." (PMID 37415158, 2023). "Moreover, KLRB1 expression exhibited a positive correlation with the expression of PDCD1 (r = 0.624), CD274 (r = 0.317), and CTLA4 (r = 0.541) under condition of tumor purity, and PDCD1 (r = 0.731), CD274 (r = 0.441), and CTLA4 (r = 0.643) under condition of age in BRCA." (PMID 37988189, 2023). "Tumor-mediated bypass of immune checkpoint inhibitor (ICI) therapy with anti-programmed death-1 (PD-1), anti-programmed death-ligand 1 (PD-L1, also called B7–H1 or CD274) or anti-cytotoxic T lymphocyte associated antigen-4 (CTLA-4) is a challenge of current years in the area of cancer immunotherapy." (PMID 38144305, 2023). "Microsatellite instability (MSI) and Tumor mutation burden (TMB) were considered to be important biomarkers in predicting the response to ICIs, which are represented by anti–programmed death-1/ligand-1 (PD-1/PD-L1) and anti–cytotoxic T lymphocyte antigen-4 (CTLA-4) inhibitors." (PMID 37981593, 2023). "Dum and colleagues identified and quantified lymphocyte subpopulations in several tumours including Pheo/PGLs by staining CTLA-4 which is an inhibitory immune checkpoint receptor and a negative regulator of anti-tumour T-cell function which could be another promising target for immunotherapy." (PMID 37033265, 2023). "Although published reports would not suggest that this might be due to reduced expression of PD-1 or CTLA-4, as these are often observed to increase with ageing, this was not the case in our experimental setting where we observed decreased levels of PD-1 and CTLA-4 on CD8+ T cells within the tumor." (PMID 37920465, 2023). "Interestingly, in several tumors, CTLA-4 was also expressed by tumor cells." (PMID 37415208, 2023). "It is suggested that anti-CTLA-4 may be considered a more effective treatment regimen due to its interference with the initial steps of T cell activation, whereas anti-PD-L1 therapy specifically targets tumor-specific T cell populations." (PMID 37046762, 2023). "Therefore, anti-CTLA-4 antibodies may produce anti-tumor effect through both CTLA-4/B7 blockage and ADCC, and other unknown mechanisms may also take effect." (PMID 36895477, 2023). "The crucial role of ICOS for anti-tumor response elicited by CTLA-4-directed ICB renders ICOS as a potential biomarker to predict CTLA-4-directed ICB response and further for the stratification of patients who may benefit from immunotherapeutic ICOS-directed treatment." (PMID 37259155, 2023). "Moreover, K1P-tumor-bearing mice were responsive to anti-PD-L1 and anti-CTLA-4 treatment." (PMID 36765792, 2023). "Therefore, we can assume that cryoablation combined with CTLA-4 or PD-1 inhibitors can enhance the anti-tumor effect and may also reverse the tumor effect." (PMID 36761748, 2023).
tumor (continued). "Importantly, in mouse models bearing primary as well as metastatic breast cancer, TMA-ARBs were shown to attenuate immunosuppression and potentiate anti-tumor T-cell activity, thereby enhancing anti-tumor response to anti-CTLA4 and anti-PD-1 combination ICI therapy." (PMID 37631380, 2023). "In addition, anti-PD-1/PD-L1 combined with anti-CTLA-4 has complementary anti-tumor mechanisms." (PMID 36845142, 2023). "In addition, CD48, CTLA4, HHLA2, TNFSF9, and TNFSF15 were elevated in high-risk group, suggesting that the high-risk group are more likely to show immunosuppressive phenotype in tumor microenvironment." (PMID 37903974, 2023). "The development of acquired resistance in FDA-approved CTLA-4 and PD-1 immunosuppressive antibodies triggers to search for additional more effective therapeutic strategies so that the efficacy of PD-1 or PD-L1 blockade pathway can enhance T cell immune response in contrast to tumor cells." (PMID 36109471, 2023). "In addition, low cuproptosis (copper-induced cell death) scores were closely associated with high tumor mutation burden, MSI-H, high CTLA4 expression, and high immune cell proportion score, indicating a novel cuproptosis-related molecular pattern to guide individualized treatment." (PMID 37325050, 2023). "Notably, first-line FLOT chemotherapy regimen upregulated CTLA-4 on the surface of T cells which might be a potential mechanism for promoting disease progression and suppressing anti-tumor immunity leading to inferior responses to neoadjuvant regiments." (PMID 37520544, 2023). "Accordingly, GDF-15 may impair long-term tumor control in patients treated with anti-CTLA-4." (PMID 37474523, 2023). "Additionally, blockage of CTLA-4 with mAbs (anti-CTLA-4) also provides a potential strategy for anticancer treatment by reducing Treg cell function that may enhance the host anti-tumor responses." (PMID 36672682, 2023). "Therefore, the tumor microenvironment could enhance the antitumor effects of anti-PD-1 or anti-CTLA-4 monoclonal antibodies against CCL20-expressing tumors in mice." (PMID 37266441, 2023). "The first group consists of ICIs inhibiting cytotoxic T lymphocyte-associated protein 4 (CTLA-4) on T cells, the second one is related to programmed cell death 1 (PD-1) receptor on lymphocytes, and the third group is linked to programmed cell death ligand 1 (PD-L1) on tumor cells." (PMID 37055532, 2023). "However, the emergence of immunotherapy, targeting PD-1/ PD-L1 and CTLA-4 pathway blockades to reverse immunosuppressive, appears to become a successful anticancer strategy and is able to induce long-term tumor remission in patients with advanced malignant tumors." (PMID 37620924, 2023). "Furthermore, CTLA‐4 is expressed by regulatory T cells (Tregs), and therapeutic anti‐CTLA‐4 antibodies may also enhance anti‐tumour immunity by depleting Tregs and neutralizing their immunosuppressive functions." (PMID 38041544, 2023). "Furthermore, the distinct mechanisms of action of PD-1 and CTLA-4 pathway blockade, along with the observed synergistic anti-tumor effects of combined treatment in preclinical models, led to the clinical evaluation of these two ICIs for cancer patients, demonstrating an enhanced clinical response." (PMID 37614504, 2023). "Additionally, signaling through other expressed immune checkpoints, such as cytotoxic T lymphocyte-associated protein 4 (CTLA-4), lymphocyte-activation gene 3 (LAG3) or T cell immunoglobulin and mucin domain 3 (TIM-3) suppresses the function of immune cells in the tumor microenvironment (TME)." (PMID 37569548, 2023). "At present, it is clinically applied immunotherapy target ICI with programmed death 1 (PD-1) 103 and cytotoxic T-lymphocyte-associated antigen 4 (CTLA-4) 104, 105, expressed in T cell surface negative direction The T cell function is regulated so that the tumor tissue is immunized." (PMID 36632233, 2023). "Inhibition of CTLA-4 may increase T-cell activity against tumor cells." (PMID 37958359, 2023).